MMP9 (matrix metallopeptidase 9)
Diseases named in the same sentence as MMP9 in open-access papers (continued):
Sharing a sentence is not in itself a finding about the gene and the disease.
preeclampsia (continued). "We selected this model since Mmp9 deletion impairs early placental development, and thus reflects “canonical” preeclampsia, rather than preeclampsia of other etiologies." (PMID 29895300, 2018). "In fact, the same investigators found that higher net activity of MMP-9, but not MMP-2, was associated with gestational hypertension, however this trend in MMP activity was absent in PE." (PMID 28143958, 2017). "High plasma levels of miR-855-5p observed in preeclampsia and the negative correlation with MMP-9 protein plasma levels open new insights to explore this miRNA as a valuable therapeutic option." (PMID 28726716, 2017). "Cardiac gene expression of Vcam, Edn1, Ccr2, Ctgf, Tgfb1, Tgfb2, Tgfb3, Bnp, Cybb, Mmp2, Mmp9, Timp1, Camk2a, Slc9a1, Nr3c2, and Nr3c1 was not different between mice who had a normal pregnancy and mice who had a preeclampsia-like pregnancy at 5 or 10 weeks postpartum (respectively)." (PMID 40425613, 2025). "This study provides evidence that the elevation of serum MMP-9 level and decline of placenta MMP-9 level may be related to the occurrence of EOPE, indicating MMP-9 may be involved in pathological and physiological process of preeclampsia." (PMID 33803206, 2021). "This study aimed at a comparative evaluation of pro-inflammatory (TNFα) and anti-inflammatory (CD206, MMP9, HGF) markers, as well as the levels of estrogen receptor α, expressed by decidual macrophages in normal pregnancy and in patients with early- and late-onset preeclampsia." (PMID 33672970, 2021). "Additionally, the potential value of maternal serum MMP-9 in first-trimester screening for preeclampsia was tested, showing no improvement in the predictive value of the model so far." (PMID 28726716, 2017). "Invasion-related genes such as transcription factor Snail, matrix metalloproteinase 2 (MMP2) and matrix metalloproteinase 9 (MMP9) have been reported to play critical roles in EVT invasion and dysregulations of these genes may contribute to the etiology of preeclampsia and IUGR." (PMID 28959722, 2017). "Measurements of the plasma levels of MMPs have not been consistent in preeclampsia: some studies show an increase in serum levels of MMP-2 and MMP-9, whereas some studies show a decreased MMP-9 level." (PMID 33482846, 2021). "We detected a higher frequency of the presence of SNPs in the NOS3 gene in the group of pregnant women with preeclampsia, but not in the MMP2 and MMP9 genes." (PMID 26317342, 2015). "Lakowska reported that decreased MMP-9 levels may be involved on pathological processes during pregnancy such as fetal growth restriction (FGR) and preeclampsia, but the results are not matched on pregnancy week." (PMID 33482846, 2021).
type 2 diabetes (58 papers, 2007 to 2026). "Studies on the connection of MMP-9 polymorphism and type 2 diabetes are two publications in which the authors focus on polymorphisms −1562 C/T (rs3918242) and +279 A/G (rs17576)." (PMID 36142480, 2022). "Moderate intensity endurance training reduced this CVD risk marker in individuals with type 2 diabetes, indicating modification of MMP-9 as one of the underlying mechanisms of exercise-induced cardiovascular protection." (PMID 35329952, 2022). "Moreover, MMP-9 polymorphisms have been associated with an increased risk of developing type 2 diabetes." (PMID 40117070, 2025). "The studies reported two single-nucleotide polymorphisms of the promoter of the MMP-9 gene, −1562 C/T (rs3918242) and +279 A/G (rs17576), as those that may be associated with the risk of developing type 2 diabetes." (PMID 36142480, 2022). "This study suggested that in patients with type 2 diabetes, the deregulation of ADAM17 and MMP9 activities in atherosclerotic plaques is associated with an impaired expression of TIMP3 via SIRT1." (PMID 38304233, 2023). "Studies have shown increased MMP-9 activity in DKD, and increased levels of MMP-9 in plasma were a risk factor for development of microalbuminuria in persons with type 2 diabetes (T2D)." (PMID 36930632, 2023). "Systemic concentrations of MMP‐2 and MMP‐9 are increased in people with type 2 diabetes and peripheral arterial disease." (PMID 33855203, 2021). "Clinical studies showed that patients with a history of coronary artery disease (CAD) and type 2 diabetes had significantly elevated serum MMP-9 levels." (PMID 22716287, 2012). "In patients with long term type 2 diabetes and suboptimal stable insulin treatment, the addition of pioglitazone but not metformin reduced the level of inflammatory biomarkers such as MMP-9 and hs-CRP and increased insulin sensitivity and adiponectin." (PMID 21756323, 2011). "Increased plasma MMP-2 and MMP-9 has also been demonstrated in persons with type 2 diabetes and peripheral arterial disease." (PMID 22363890, 2011). "Although MMP-9 seems to reflect an overall burden of vascular disease in type 2 diabetes patients it is still controversially discussed to use it as a reliable surrogate marker of CV risk to date." (PMID 21756323, 2011). "Power assuming α = 0.05 and relative risk of 1.4 was 62%, 83%, 85% and 79% for type 2 diabetic patients with diabetic nephropathy for IL8, CCL2, CCR5, MMP9 polymorphisms (p<0.05) among North Indian population." (PMID 19357773, 2009). "Furthermore, it has been shown that increased plasma level of MMP-9 predicted the appearance of microalbuminuria in noninsulin-dependent diabetes mellitus." (PMID 23922934, 2013). "In addition, levels of MMP-9 were reduced after treatment of linagliptin, an inhibitor for dipeptidyl peptidase-4 enzyme to attenuate aberrant biosynthesis and secretion of insulin to treat Type 2 diabetes." (PMID 25859655, 2015). "There were evidences for the association of MMP9 with type 2 diabetes, but not the case for MMP8." (PMID 26252209, 2015). "In addition, previously published data indicate that metformin treatment decreases matrix metalloproteinase (MMP)-9 in drug naive diabetic patients and improves endothelial function in patient with type 2 diabetes as well as first-degree relatives of type 2 diabetic patients." (PMID 22676459, 2012). "Thus, as shown in our study, the reduction of MMP2 and MMP9 may be a possible mechanism in preventing macrovascular complications in patients with type 2 diabetes by sitagliptin treatment." (PMID 22493727, 2012). "Authors showed that at level of human carotid atherosclerotic plaques, TIMP3 was significantly impaired in patients with type 2 diabetes, leading to A Disintegrin And Metalloproteinase (ADAM17) and MMP9 overactivity." (PMID 38304233, 2023). "In the direct case of type 2 diabetes, the previous reports mention two enzymes from this family: MMP-2 and MMP-9." (PMID 36142480, 2022).
type 2 diabetes (continued). "The impact of type 2 diabetes on levels of salivary MMP-8, MMP-9, RANKL, and OPG was also investigated." (PMID 26989414, 2016). "Despite these limitations, these data suggests that LDL from subjects with Type 2 diabetes promotes increased monocyte mRNA expression of MMP-1, MMP-9, and ADAM proteinases responsible for inflammatory cytokine and adhesion molecule shedding." (PMID 17714581, 2007). "In vitro, Type 2 diabetes LDL promoted the expression of the MMP-1, MMP-9, ADAM28, ADAM17 and ADAM15 genes compared to control LDL." (PMID 17714581, 2007). "We tested the hypothesis that type 2 diabetes adversely influences the prevalence of the periodontal pathogens investigated and the levels of salivary MMP-8, MMP-9, RANKL, and OPG." (PMID 26989414, 2016). "Also high levels of MMP-9 and TIMP-2 have been found in patients with an acute coronary syndrome and type 2 diabetes, probably reflecting an abnormal extracellular matrix metabolism in these patients." (PMID 20809989, 2010). "The main finding of the present study is an increase in serum MMP-9 and MIF concentrations in healthy nonobese subjects with family history of type 2 diabetes." (PMID 30302090, 2018). "Our data show that type 2 diabetes has no significant influence on the prevalence of the investigated periodontal pathogens, or the levels of salivary MMP-8, MMP-9, and OPG." (PMID 26989414, 2016). "Moreover, we were unable to detect a significant difference in levels of salivary MMP-8, MMP-9, and OPG between individuals with and without type 2 diabetes." (PMID 26989414, 2016).
schizophrenia (57 papers, 2009 to 2025). A major psychotic disorder characterized by abnormalities in the perception or expression of reality. "Meanwhile, dysregulation of MMP-9 has been linked to multiple disorders, including schizophrenia, autism spectrum disorders, and epilepsy." (PMID 38605069, 2024). "In the case of this disease, more research is needed to examine the relationship between the MMP-9-1562C/T polymorphism and the risk of developing schizophrenia." (PMID 37206663, 2023). "Another study of treatment outcome found that genetic variation (SNP in the MMP9 gene) was associated with the risk of developing treatment-resistant schizophrenia, with an additional interaction effect with experiences of childhood trauma." (PMID 37144963, 2023). "To further clarify the role of BDNF and MMP-9 genes as risk alleles or regulators of schizophrenia, we carried out this case-control association study between BDNF rs6265 and MMP-9 rs3918242 SNPs." (PMID 36325525, 2022). "The objectives of this study are to determine the possible association between schizophrenia and toxoplasmosis and highlight the existence of gene polymorphism encoding MMP-9 protein’s in patients presented both schizophrenia and toxoplasmosis." (PMID 32460746, 2020). "Recent studies have identified MMP-16 as a schizophrenia risk gene, and MMP-9 and ADAMTS-5 are implicated in schizophrenia and cerebral cavernous malformations, respectively." (PMID 33143303, 2020). "The present study investigated the effects of low MMP-9 activity on the predisposition to schizophrenia-like symptoms in mice that were subjected to psychosocial stress." (PMID 31555105, 2019). "To investigate the possible role of environmental factors that act in concert with Mmp-9-dependent genetic predisposition in schizophrenia, we studied Mmp-9 heterozygous knockout mice with low MMP-9 activity." (PMID 31555105, 2019). "The present study describes a novel mouse model of schizophrenia-related gene × environment interactions that involves the risk gene Mmp-9." (PMID 31555105, 2019). "Low brain levels of MMP-9 appear to be a risk factor for schizophrenia, in which gene × environment interactions that involve Mmp-9 contribute to the pathophysiology of this neuropsychiatric disorder." (PMID 31555105, 2019). "In conclusion, the present study validated the association between MMP-9 and schizophrenia symptoms." (PMID 31555105, 2019). "Matrix metalloproteinase-9 (MMP-9) has been previously implicated in the pathophysiology of schizophrenia." (PMID 31555105, 2019). "DS patients showed a specific abnormality of peripheral MMP9 expression and DNA methylation, indicating a pathological mechanism underlying DS as a specific subgroup of schizophrenia." (PMID 30619470, 2018). "Lower methylation at several individual CpG sites and higher MMP9 expression was associated with higher SANS scores in schizophrenia patients in the present study." (PMID 30619470, 2018). "Matrix metalloproteinase 9 (MMP‐9) has recently emerged as a molecule that contributes to pathological synaptic plasticity in schizophrenia, but explanation of the underlying mechanisms has been missing." (PMID 28623238, 2017). "In summary, our results link MMP‐9 gene polymorphisms with a specific subphenotype of schizophrenia, suggesting that the underlying mechanism depends on the local synthesis of MMP‐9 within the vicinity of excitatory synapses." (PMID 28623238, 2017). "In the present study, we identify a novel function of rs20544 C/T SNP that is located in the 3′UTR of MMP‐9, and we show that it is strongly associated with the severity of a chronic delusional syndrome in schizophrenia patients." (PMID 28623238, 2017). "In the present translational study, we report an association between the MMP‐9 rs20544 C/T single‐nucleotide polymorphism (SNP) in the 3′untranslated region (UTR) with the severity of schizophrenia symptoms." (PMID 28623238, 2017).
schizophrenia (continued). "To date, studies on MMP-9 polymorphisms have indicated an association with a number of tumors, cardiovascular disease, autoimmune diseases, schizophrenia and stomatitis." (PMID 25667675, 2015). "Our results showed that alterations of plasma OS parameters in male patients with chronic schizophrenia were associated with psychopathology and MMP-9, suggesting that OS and neuroinflammation may play important role in the mechanism of schizophrenia." (PMID 38172869, 2024). "MMP-9 gene polymorphism has been associated with schizophrenia." (PMID 37692299, 2023). "Two studies were performed, the first, to determine the possible association between schizophrenia and toxoplasmosis and the second, to highlight the existence of gene polymorphism encoding a proinflammatory protein MMP-9 in patients with schizophrenia and infected with Toxoplasma." (PMID 32460746, 2020). "Toxoplasmosis may be one of the etiological causes of schizophrenia, and MMP-9 gene polymorphism could be involved in the occurrence mechanism of this pathology following Toxoplasma infection." (PMID 32460746, 2020). "In the molecular study, small sample size and the lack of a control group were noted it would, therefore, be interesting to do the case-control study to confirm the association of the polymorphism of the MMP-9 gene with T. gondii infection and the occurrence of schizophrenia." (PMID 32460746, 2020). "Similarly, upregulated MMP-9 serum levels were found to be strongly associated with levels of mature BDNF (MMP-9 aids in the formation of mature BDNF from pro-BDNF) in schizophrenia patients." (PMID 31172215, 2019). "Lower MMP-9 levels in the brain might be a risk factor for schizophrenia that, in combination with environmental factors (e.g., psychosocial stress), may evoke schizophrenia-like symptoms that are sensitive to antipsychotic treatment." (PMID 31555105, 2019). "Importantly, studies of MMP-9 genetic polymorphisms in human schizophrenia patients have shown that the gene variants predisposing to lesser MMP-9 expression confer higher disease risk." (PMID 31555105, 2019). "MMP9 C1562T gene promoter polymorphism has been shown to associate with schizophrenia." (PMID 31172215, 2019). "Notably, network analysis placed Lox, Mmp9 and Tgfb1 at the core of the astroglial networks associated with AD (Fig. 3aii) and schizophrenia (Fig. 3bii)." (PMID 31477687, 2019). "A functional polymorphism of the MMP-9 gene was discovered in human schizophrenia patients." (PMID 30123106, 2018). "The association between gene polymorphism and behavioral symptoms in schizophrenia might provide a mechanistic insight into MMP9 gene function." (PMID 30619470, 2018). "Schizophrenia is associated with higher MMP-9/TIMP1 ratios compared to healthy controls." (PMID 30123106, 2018). "Moreover, two independent studies found association of MMP‐9 promoter polymorphism −1562C/T (rs3918242) with schizophrenia." (PMID 28623238, 2017). "Moreover, the chromosome region 20q11‐13, where the MMP‐9 gene is located, has been linked to schizophrenia." (PMID 28623238, 2017). "It has also been reported that the MMP-9 gene polymorphisms are associated with cardiovascular disease and neuropsychiatric disorders, including schizophrenia, and bipolar disorder, suggesting that this enzyme may be a pathological mediator in these diseases." (PMID 22880079, 2012). "Furthermore, clinical studies of MMP-9 in schizophrenia (plasma levels as well as gene polymorphisms) have shown that both higher and lower levels of the enzyme may be associated with the disease." (PMID 37004521, 2023). "Thus gene polymorphism and alterations of MMP9, both down- as well as up-regulated, might be possible factors contributing to the pathophysiological underpinning of schizophrenia." (PMID 30619470, 2018). "Our finding showed a significant increase of MMP-9 levels in patients with schizophrenia, when compared with healthy controls, which is consistent with previous studies." (PMID 38172869, 2024).